CREB3L1 (cAMP responsive element binding protein 3 like 1)
Description:
[Cyclic AMP-responsive element-binding protein 3-like protein 1]: Precursor of the transcription factor form (Processed cyclic AMP-responsive element-binding protein 3-like protein 1), which is embedded in the endoplasmic reticulum membrane with N-terminal DNA-binding and transcription activation domains oriented toward the cytosolic face of the membrane. In response to ER stress or DNA damage, transported to the Golgi, where it is cleaved in a site-specific manner by resident proteases S1P/MBTPS1 and S2P/MBTPS2. The released N-terminal cytosolic domain is translocated to the nucleus where it activates transcription of specific target genes involved in the cell-cycle progression inhibition. [Processed cyclic AMP-responsive element-binding protein 3-like protein 1]: Transcription factor involved in cell type specific DNA damage and unfolded protein response (UPR). Binds the DNA consensus sequence 5'-GTGXGCXGC-3'. Plays a critical role in bone formation through the transcription of COL1A1, and possibly COL1A2, and the secretion of bone matrix proteins. Directly binds to the UPR element (UPRE)-like sequence in an osteoblast-specific COL1A1 promoter region and induces its transcription. Does not regulate COL1A1 in other tissues, such as skin (By similarity). Required to protect astrocytes from ER stress-induced cell death. In astrocytes, binds to the cAMP response element (CRE) of the BiP/HSPA5 promoter and participate in its transcriptional activation (By similarity). In astrocytes and osteoblasts, upon DNA damage, inhibits cell-cycle progression after G2/M phase by binding to promoters and activating transcription of genes encoding cell-cycle inhibitors, such as p21/CDKN1A (By similarity). Required for TGFB1 to activate genes involved in the assembly of collagen extracellular matrix. (Microbial infection) May play a role in limiting virus spread by inhibiting proliferation of virus-infected cells. Upon infection with diverse DNA and RNA viruses, inhibits cell-cycle progression by binding to promoters and activating transcription of genes encoding cell-cycle inhibitors, such as p21/CDKN1A.
Synonyms: OASIS; C16DELp11.2; DEL16p11.2; OI16
Tractability: Antibody: UniProt predicts a signal peptide or a membrane-spanning region. PROTAC: UniProt records ubiquitination sites on it; ubiquitination databases record sites on it.
Gene: Protein-coding gene on chromosome 11 (46,277,637 to 46,321,422, forward strand). Ensembl gene ENSG00000157613.
Subcellular location: Endoplasmic reticulum membrane (Cyclic AMP-responsive element-binding protein 3- like protein 1); Nucleus (Processed cyclic AMP-responsive element-binding protein 3-like protein 1)
Subcellular location (Human Protein Atlas): Nucleoplasm; Cytosol
Pathways (Reactome):
Cellular responses to stimuli: CREB3 factors activate genes
Gene Ontology:
Molecular function: DNA-binding transcription repressor activity, RNA polymerase II-specific; protein binding; sequence-specific double-stranded DNA binding; SMAD binding; cAMP response element binding; chromatin binding; DNA-binding transcription activator activity, RNA polymerase II-specific; DNA-binding transcription factor activity, RNA polymerase II-specific; transcription cis-regulatory region binding; DNA-binding transcription factor activity
Biological process: negative regulation of DNA-templated transcription; negative regulation of fibroblast growth factor receptor signaling pathway; negative regulation of gene expression; negative regulation of sprouting angiogenesis; positive regulation of collagen biosynthetic process; endoplasmic reticulum unfolded protein response; extracellular matrix constituent secretion; negative regulation of endoplasmic reticulum stress-induced intrinsic apoptotic signaling pathway; osteoblast differentiation; positive regulation of transcription by RNA polymerase II; regulation of transcription by RNA polymerase II; response to endoplasmic reticulum stress; negative regulation of transcription by RNA polymerase II; regulation of DNA-templated transcription
Cellular component: chromatin; endoplasmic reticulum; endoplasmic reticulum membrane; membrane; nucleus
Genetic constraint (gnomAD): Loss-of-function variants: 28 observed, 40.25 expected, observed/expected ratio (o/e) 0.7, 90% interval 0.51 to 0.95. The upper end of that interval is the gene's LOEUF score, 0.95, which puts it in group 4 of 6, group 1 being the genes least tolerant of losing a copy. Missense variants: 628 observed, 588.38 expected, observed/expected ratio (o/e) 1.07, 90% interval 1 to 1.14. Synonymous variants: 272 observed, 251.73 expected, observed/expected ratio (o/e) 1.08, 90% interval 0.98 to 1.2.
Cancer hallmarks: angiogenesis (suppresses); invasion and metastasis (suppresses)
Homologues: Orthologues: chimpanzee CREB3L1 (99% identical), macaque CREB3L1 (98% identical), dog CREB3L1 (95% identical), pig CREB3L1 (95% identical), mouse Creb3l1 (92% identical), guinea pig CREB3L1 (91% identical), rat Creb3l1 (91% identical), rabbit CREB3L1 (86% identical), zebrafish creb3l1 (59% identical), tropical clawed frog CREB3L1 (55% identical), Drosophila melanogaster CrebA (29% identical), Caenorhabditis elegans crh-2 (17% identical), and 4 more. Paralogues in human: CREB3L2 (44% identical), CREB3L3 (22% identical), CREB3 (19% identical), CREB3L4 (19% identical), ATF6B (17% identical), ATF6 (16% identical), CREB1 (11% identical), ATF1 (10% identical), CREM (10% identical).
Diseases named in the same sentence as CREB3L1 in open-access papers:
CREB3L1 is named in the same sentence as 136 diseases in open-access papers, as found by Europe PMC text mining. Sharing a sentence is not in itself a finding about the gene and the disease. The quoted sentences say what the papers report.
breast carcinoma (25 papers, 2012 to 2025). "Low CREB3L1 expression is associated with high-grade metastatic breast cancers with poor prognosis, specifically TNBC." (PMID 40427627, 2025). "We have shown that CREB3L1 loss directly contributes to the metastatic phenotype of breast cancer cells, using in vitro cell-based assays and animal models of breast cancer." (PMID 36123435, 2022). "Two luminal A (HCC1428, T47D) and two basal TNBC (HCC1806, HCC70) CREB3L1-deficient breast cancer cell lines were characterized as compared to their corresponding HA-CREB3L1-expressing counterparts." (PMID 35802566, 2022). "Since loss of CREB3L1 is prevalent in ~ 75% of TNBCs and this loss contributes to metastatic breast cancer cell properties, we focused on identifying compounds most cytotoxic towards the more metastatic CREB3L1-deficient TNBCs." (PMID 36123435, 2022). "CREB3L1-deficient breast cancers are typically the more advanced metastatic breast tumors and include ~ 75% of TNBCs15." (PMID 36123435, 2022). "CREB3L1 is a metastasis suppressor in breast cancer and low CREB3L1 expression is associated with poor prognosis in both TNBC and luminal A breast cancers." (PMID 36123435, 2022). "DCK is also overexpressed in poor outcome breast cancers, including the metastatic CREB3L1-deficient breast cancer cell lines (HCC1954, BT474, SK-BR-3, MDA-MB-231, MCF7, and T47D) and has low expression in the non-tumorigenic breast cell line MCF10A12,33." (PMID 36123435, 2022). "In this report, we set out to determine the contribution of CREB3L1-deficiency to the oncogenic cell properties in human breast cancer cells specifically of the luminal A and TNBC subtypes." (PMID 35802566, 2022). "Expression of HA-CREB3L1 was sufficient to reduce both cell migration and colony formation in soft agar in CREB3L1-deficient human breast cancer cell lines." (PMID 35802566, 2022). "In keeping with our results, mutations in SNPs rs1269851 (ATF6B gene) and rs35652107 (CREB3L1 gene) modify the number of births – breast cancer relationship." (PMID 29530003, 2018). "This study demonstrates that the low CREB3L1 expression previously seen in highly metastatic breast cancer cell lines is caused in part by epigenetic silencing." (PMID 26810754, 2016). "Previous investigations by our laboratory have implicated CREB3L1 as a metastatic suppressor gene in breast cancer models in vitro and in vivo." (PMID 26810754, 2016). "According to the Catalogue of Somatic Mutations in Cancer (COSMIC) database, CREB3L1 is rarely mutated in cancers but shows reduced copy number in 18 % (140/782) of breast cancers." (PMID 26810754, 2016). "Several luminal A breast cancer cell lines are similarly CREB3L1-deficient." (PMID 35802566, 2022). "Interestingly, the activin-SMAD pathway, a downstream target of CDK4/6 (independent of Rb) was shown to be a good target for palbociclib in CREB3L1-deficient T47D luminal A breast cancer cells." (PMID 36123435, 2022). "All four parental CREB3L1-deficient breast cancer cell lines formed numerous colonies in soft agar." (PMID 35802566, 2022). "Further, we have identified a small subset of luminal A breast cancers (7–24%) that are CREB3L1-deficient, suggesting that this subgroup of luminal A breast cancers is likely to be more metastatic and could be identified and treated with chemotherapy agents to improve the outcomes of these patients." (PMID 35802566, 2022). "In other studies, ER stress was shown to induce anti-angiogenesis signaling via IRE1α and PERK pathway in the retina, CHOP in hind-limb ischemia, and CREB3L1 in mammary tumor model." (PMID 40136669, 2025). "Further emerging evidences are highlighting the pathological functions of abnormally expressed CREB3L1 in the occurrence, progress, and prediction of patients with glioma, breast cancer, and thyroid cancer." (PMID 38164349, 2024). "CREB3L1 can work to facilitate breast cancer metastasis through mediating the prometastatic signaling of PERK, especially for TNBCs." (PMID 38164349, 2024).
breast carcinoma (continued). "In breast cancer cells, overexpression of CREB3L1 in LN4D6 and MDA-MB-435 significantly diminishes cell migration and invasion." (PMID 38164349, 2024). "Overall, the majority of breast cancers show increased CREB3L1 expression as compared to normal breast tissue, however ~30% of breast cancers show decreased CREB3L1 expression as a result of epigenetic silencing." (PMID 35802566, 2022). "HCC1428 luminal A breast cancer cells showed increased drug sensitivity to both palbociclib isethionate and cladribine as compared to the corresponding CREB3L1-expressing cells, however the opposite was true for lanatoside C and homoharringtonine." (PMID 36123435, 2022). "We previously analyzed a large panel of human breast cancer cell lines and determined their endogenous CREB3L1 protein expression." (PMID 35802566, 2022). "The CREB3L1 expression in luminal B breast cancers (median 8.4) was similar to that in normal breast tissue." (PMID 35802566, 2022). "Using this model system, knockdown of CREB3L1 in CREB3L1-expressing breast cancer cells resulted in increased cell migration, invasion and anchorage-independent growth in soft agar." (PMID 35802566, 2022). "Most strikingly, TNBCs had the lowest CREB3L1 expression (median 6.9), significantly lower than all other subtypes of breast cancer as well as normal breast tissue (p < 0.0001)." (PMID 35802566, 2022). "Mechanistically, CREB3L1 can promote breast cancer cell invasion and metastasis through inducing ECM production by activating FAK, and a chemical inhibitor of proteases, AEBSF can inhibit breast cancer cell invasion by inhibiting CREB3L1 expression." (PMID 36171879, 2022). "In this report, we provide additional evidence supporting a metastasis suppressor role for CREB3L1 in two human estrogen-dependent luminal A breast cancer cell lines (HCC1428 and T47D), as well as two TNBC cell lines (HCC1806 and HCC70)." (PMID 35802566, 2022). "In a study of breast cancer, it was suggested that Creb3l1 was a target of downstream effector ATF4." (PMID 35803572, 2022). "Our findings are consistent with the survival data showing that both luminal A and TNBC breast cancer patients with CREB3L1-low tumors have a significantly worse prognosis, as compared to similar patients with CREB3L1-high tumors." (PMID 35802566, 2022). "This database provided CREB3L1 mRNA expression levels for a large number of breast tumor tissues classified into breast cancer subtypes: luminal A (ER+, PR±, HER2-), luminal B (ER+, PR±, HER2+), HER2 and TNBC (ER-, PR-, HER2-) as well as normal breast tissue." (PMID 35802566, 2022). "CREB3L1 expression is frequently upregulated in early breast cancers, but its expression is significantly reduced in more advanced and metastatic breast cancers due to epigenetic silencing." (PMID 36123435, 2022). "In human breast tumor samples, about 30% have low levels of CREB3L1, primarily due to epigenetic silencing, which is also observed in breast cancer cell lines." (PMID 35802566, 2022). "We have been studying a member of CREB3-family, CREB3L1 (cAMP-responsive element binding protein 3 like 1), a transcription factor responsible for repressing the expression of genes that promote breast cancer progression and metastasis." (PMID 36123435, 2022). "To assess CREB3L1 expression in different breast cancer subtypes as compared to normal breast tissue, we accessed the Gene Expression database of Normal and Tumor tissues 2 (GENT2)." (PMID 35802566, 2022). "PERK's prometastatic functions in breast cancer were mediated by its downstream transcription factor CREB3L1." (PMID 33937330, 2021).
breast carcinoma (continued). "In breast cancer, CREB3L1 is greatly up-regulated, which leads to enhanced metastasis and poor prognosis." (PMID 31121863, 2019). "We found that genetic variants in RPS6KA1, ATF6B, CREB3L1 and SRC genes were associated with modified relationships between reproductive factors and breast cancer, especially the protective effect of the number of deliveries and the early age at menopause." (PMID 29530003, 2018). "Previous reports have indicated that expression of CREB3L1 is frequently epigenetically silenced through DNA methylation in various cancers including breast cancer." (PMID 30103710, 2018). "To functionally assess CREB3L1’s role in regulating these genes, we used shRNAs to stably inhibit CREB3L1 expression in two invasive breast cancer cell lines, SUM159 and MDA.MB.231." (PMID 29057869, 2017). "We next assessed CREB3L1’s role in vivo using the MDA.MB.231-LM2 orthotopic transplantation model of human breast cancer, which forms tumors that invade the vasculature and metastasize to the lungs." (PMID 29057869, 2017). "Here, the authors find that CREB3L1 is required for PERK's pro-metastatic function in breast cancer, and its inhibition suppresses cancer invasion and metastasis." (PMID 29057869, 2017). "Here we identify the transcription factor CREB3L1 as an essential mediator of PERK’s pro-metastatic functions in breast cancer." (PMID 29057869, 2017). "To assess the clinical relevance of these findings, we examined CREB3L1 expression in primary breast cancers and metastatic breast cancers from patients." (PMID 29057869, 2017). "In contrast, both luminal A (ER+ and/or PR+, HER2–, low Ki67) and triple negative breast cancer patients with low CREB3L1 mRNA expression had higher HRs (1.49 and 1.33, respectively) that were statistically significant (p <0.00001 and p <0.05, respectively)." (PMID 26810754, 2016). "We analyzed CREB3L1 mRNA expression in a large panel of 40 breast cancer cell lines using quantitative real-time PCR (qPCR)." (PMID 26810754, 2016). "Here we have expanded upon our previous study to include 40 human breast cancer cell lines and over 200 human breast cancer tumor samples and investigated DNA methylation and its role in the regulation of CREB3L1 expression." (PMID 26810754, 2016). "In parallel, luminal breast cancers with nuclear CREB3L1 were most frequently of low-medium grade, whereas those with cytoplasmic CREB3L1 were often high-grade tumors." (PMID 26810754, 2016). "CREB3L1 is located on chromosome 11, a chromosome that contains a number of loci that are frequently altered in breast cancer." (PMID 26810754, 2016). "Increased CREB3L1 gene methylation and low CREB3L1 mRNA expression were both correlated with more aggressive types of breast cancer and higher tumor grade (8 and 9)." (PMID 26810754, 2016). "Our results also show that reduced CREB3L1 mRNA is an indicator of poor prognosis, specifically in luminal A breast cancer and TNBC." (PMID 26810754, 2016). "Our analysis also found that breast cancer patients with low CREB3L1 expression have a shorter relapse-free survival time specifically for the luminal A and TNBC subtypes." (PMID 26810754, 2016). "Our data further strengthens the role for CREB3L1 as a metastasis suppressor in breast cancer and demonstrates that epigenetic silencing is a major regulator of the loss of CREB3L1 expression." (PMID 26810754, 2016). "This suggests that low CREB3L1 is a marker for poor prognosis in both luminal A breast cancer and TNBC." (PMID 26810754, 2016). "Treatment of several highly metastatic breast cancer cell lines that had low CREB3L1 expression with DNA methyltransferase and histone deacetylase inhibitors induced expression of CREB3L1, both mRNA and protein." (PMID 26810754, 2016). "In a rat model of breast cancer, CREB3L1-re-expressing cells initially formed large tumors (>0.5 cm3), in which 70 % of them regressed to a nearly undetectable size." (PMID 26810754, 2016).